INS (insulin)
Diseases named in the same sentence as INS in open-access papers (continued):
Sharing a sentence is not in itself a finding about the gene and the disease.
Hypoglycemia (continued). "The majority of cells were A, alpha cells that secrete glucagon (a polypeptide hormone secreted in response to hypoglycemia or growth hormone stimulation); or B, beta cells that secrete insulin into the bloodstream in response to a rise in concentration of blood glucose or amino acids." (PMID 37663296, 2023). "Moreover, in hospitalized patients, treatment with DPP-4 inhibitors has been associated with similar glycemic control, and lower rates of hypoglycemia compared with insulin regimens." (PMID 36964858, 2023). "In any insulin therapy, due to its physiological role as an anabolic hormone that promotes the uptake and storage of glucose by cells, there is always an inherent delicate balance between achieving good blood sugar control, hypoglycemia, and weight change." (PMID 38206709, 2023). "Hence, a shift in the dynamics of insulin secretion seems to best explain the occurrence of late post-prandial or oral glucose load hypoglycaemia in CF." (PMID 37720541, 2023). "However, two studies evaluated peak GH level variability using insulin, and both concluded that the time after insulin injection determines the severity of hypoglycemia, with durations less than 90 minutes indicating safety and cost-effectiveness." (PMID 37628380, 2023). "Although LGA is believed to be related to increased fetal insulin production resulting in increased growth, it had a distinct metabolite profile when compared with neonatal hypoglycaemia and cord blood C-peptide, considered an indirect and direct assessment of neonatal hyperinsulinism, respectively." (PMID 37615689, 2023). "Also, under classical intensive insulin therapy, an incompressible hypoglycemia frequency (estimated at 5–15% of total glucose values) is unavoidable to maintain mean glycemia within targets." (PMID 38033011, 2023). "Obstacles may include limited access to insulin or monitoring tools, necessity for additional caregiver and patient training, or the fear of hypoglycemia." (PMID 37476884, 2023). "It is generally recommended to reduce basal insulin doses after exercise to reduce the risk of post-exercise nocturnal hypoglycaemia." (PMID 36879098, 2023). "However, under pathogen-free conditions, these mice manage to survive and demonstrate increased insulin sensitivity, hypoglycemia, reduced fasting insulin levels, normal body weight, and unaltered fat mass." (PMID 38317714, 2023). "Almost all studies on insulin therapy demonstrate the side effect of hypoglycemia." (PMID 37242426, 2023). "Hypoglycemia (<54 mg/dL or severe) was reported in five (1%) patients at the 5 mg dose, four (1%) at the 10 mg dose, and eight (2%) at the 15 mg dose, compared with 26 (7%) to insulin degludec." (PMID 37445623, 2023). "Typically, glucagon reverses hypoglycemia; however, in patients with pancreatogenic diabetes, a small insulin overdose resulting in hypoglycemia may be life-threatening." (PMID 36945494, 2023). "Comparison between the three study groups at the end of the study revealed significantly lower HbA1c (p = 0.002), frequency of hypoglycemia (p = 0.006), and severe hypoglycemia (p = 0.029) in the insulin degludec and insulin glargine groups compared to the NPH group." (PMID 36800034, 2023). "As is also evident from hypoglycaemia management in clinical practice, inter- and intraindividual differences in carbohydrate requirements exist depending on initial glucose concentration, preceding physical activity, insulin on board and other variables." (PMID 37037948, 2023). "However, in a sensitivity analysis of the counterregulatory hormone responses that only included individuals who experienced hypoglycaemia for both insulin products, numerical results comparable to the main statistical analyses were obtained." (PMID 37308751, 2023). "Importantly, although the ‘dead in bed’ syndrome has been described in T1D, hypoglycemia-induced fatal arrhythmias are also likely to occur in patients with insulin-treated T2D." (PMID 37298308, 2023).
Hypoglycemia (continued). "If sensor glucose values are predicted to drop or rise, the algorithm can automatically reduce or increase basal insulin infusion to totally suspend in case of predicted hypoglycemia (<70 mg/dL) or to release correction boluses in case of hyperglycemia (>180 mg/dL)." (PMID 36983941, 2023). "Hypoglycaemia towards lunchtime was combated by pre‐emptive short‐term suspension of basal insulin." (PMID 37562398, 2023). "For metastatic insulinoma, primary tumor should be resected to improve the life quality, and metastasis also need to be removed because the tumors could secrete excess insulin resulting in hypoglycemia symptoms." (PMID 37251916, 2023). "In this case, the hypoglycemia was unlikely due to insulin overdose." (PMID 38134112, 2023). "This study examined the acceptability and psychometric properties of an innovative smartphone app (Hypo-METRICS): results of the present study support its use as an innovative research tool to determine the impact of hypoglycemia on daily functioning among adults with T1DM or T2DM using insulin." (PMID 36930585, 2023). "Indeed, hypoglycemia can be a direct consequence of the use of medicines such as insulin and oral antidiabetic agents such as sulfonylureas and methyglinides." (PMID 37111265, 2023). "In addition, insulin pump therapy allows for more flexible insulin dosing and timing, which can lead to better glycemic control and fewer episodes of hypoglycemia." (PMID 37485197, 2023). "Moreover, crude methanol extract and fractions produced pronounced hypoglycemia when co-administered with 3 units of insulin." (PMID 37110767, 2023). "Hypoglycemia was less frequent in patients who received oral antidiabetics that are unlikely to cause hypoglycemia, even in those who were also treated with insulin." (PMID 38044455, 2023). "Thus, the use of insulin degludec and glargine is recommended in toddlers and preschoolers with T1D owing to their better glycemic control with reduced risk of hypoglycemia and lower IDD than NPH insulin." (PMID 36800034, 2023). "A sweet taste induces an insulin response, which causes blood sugar to be stored in tissues, but because blood sugar does not increase with artificial sweeteners, there is hypoglycemia and increased food intake." (PMID 37109657, 2023). "More insulin-treated patients had ischaemic heart disease (46.7% vs. 33.6%, p = 0.028), diabetic foot disease (15.6% vs. 4.8%, p = 0.003), retinopathy (40.2% vs. 11.0%, p < 0.001), and emergency attendance for severe hypoglycaemia (3.8% vs. 0% p = 0.042)." (PMID 37152098, 2023). "Two (22%) of the nine participants with hypoglycaemia and not on insulin were at risk of malnutrition." (PMID 37817166, 2023). "High levels of IGF-II also suppress normal insulin secretion by pancreatic beta-cells, which may lead to postprandial hyperglycemia in the context of fasting hypoglycemia." (PMID 37630734, 2023). "Thus, the present work should promote many other studies aiming to characterize the importance of insulin and hypoglycaemia in determining carotid body function and cardiorespiratory control in physiology and pathology." (PMID 36651857, 2023). "The pathogenesis of hypoglycemia in PA is multifactorial involving severe glycogen depletion secondary to catecholamine release, reduced glucagon response, increased insulin release, and reduced adiponectin (which promotes insulin sensitivity)." (PMID 37929024, 2023). "Thus, each of these three inputs to the ghrelin cell – namely, glucose, insulin, and sympathetic nervous system activity – likely plays a balanced part in determining the amount of ghrelin released upon insulin-induced hypoglycemia." (PMID 37334290, 2023). "Overall for GDM, 2 h-OGTT, gestational age at birth, neonatal hypoglycemia outcomes the heterogeneity was high, while for insulin therapy, C-section rate, neonatal intensive care unit admission, preterm birth, shoulder dystocia and gestational hypertension outcomes, it was low." (PMID 37836508, 2023).
Hypoglycemia (continued). "Clearance of bioactive insulin from antibody‐bound reservoirs may be sufficiently retarded to produce sustained hypoglycaemia for days following cessation of exogenous insulin even in those with endogenous insulin deficiency." (PMID 37562398, 2023). "Similarly, overexpression of PL in β-cells resulted in fasting and postprandial hypoglycemia, marked elevated serum insulin levels, increased islet insulin granules and volume and increased β-cell numbers and proliferation." (PMID 36993818, 2023). "Therefore, counseling about the risk of hypoglycemia and steps to recognize, prevent, and treat hypoglycemia has been recommended for all patients for whom initiation of insulin is planned." (PMID 36650625, 2023). "Consequently, a suggested reduction in basal insulin rates of approximately 10–20% during weeks 8–16, especially during nocturnal hours to forestall hypoglycemia, is recommended." (PMID 38068755, 2023). "However, the incidence of severe hypoglycemia in patients with T2D who have been treated with insulin for >5 years increases and approaches that of patients with T1D." (PMID 37298308, 2023). "Owing to the high risk of hypoglycemia and reduced renal clearance in people with T2DM and chronic kidney disease (CKD), an insulin treatment that decreases glycated hemoglobin (HbA1c) without escalating the risk of hypoglycemia is clinically important." (PMID 36624651, 2023). "Three of our patients (Patient 11 with a heterozygous ABCC8 variant, patient 16 with a maternally inherited INS variant, and patient 30 with a heterozygous GCK variant) presented with hypoglycemia in the neonatal period (patient 11 presented with hypoglycemic coma)." (PMID 36398453, 2023). "Sulfonylureas and insulin are associated with an increased hypoglycemia risk and would not be preferred for patients in whom this is a concern." (PMID 36845056, 2023). "Also, the rise in plasma levels of two CRR hormones normally observed following a single episode of hypoglycemia (30 min following insulin administration) was significantly attenuated in the “Recurrent Hypo” mice." (PMID 37334290, 2023). "However, serum insulin and C-peptide levels checked during the hypoglycemia were within normal ranges." (PMID 38134112, 2023). "Surprisingly, plasma glucose increased significantly more upon glucagon challenge in the group of rats in which hypoglycaemia was induced using GCGRi–insulin (p<0.001), and plasma glucose was elevated for a longer time compared with animals in which hypoglycaemia was induced using HI." (PMID 36404376, 2023). "Fasted serum insulin was low concurrently with severe hypoglycemia." (PMID 37065226, 2023). "Importantly, when rapid weight loss is observed after SGLT2i medication administration, as well as a positive effect related to improvements in insulin resistance, attention must also be paid to an increased frequency of hypoglycemia." (PMID 37424302, 2023). "CLP-induced attenuation of IRS tyrosine phosphorylation might result from either hypoglycemia or low levels of endogenous insulin." (PMID 37550630, 2023). "In instances where mild hypoglycemia may manifest, its frequency and severity can be ameliorated via suitable insulin reduction, heightened monitoring frequency, and the prompt cessation of fasting upon the emergence of hypoglycemic episodes." (PMID 38068755, 2023). "The attenuated dynamics of SY and PASY activity during hypoglycemia in individuals who are overweight and insulin-resistant may potentially contribute to elevated glucose, although mechanisms are not understood." (PMID 36752854, 2023). "Current definitions and biomarkers used to identify partial remission (i.e., residual secretion or IDAA1C score) either require invasive blood sampling or present several limitations to describe the evolution of glycemic homeostasis (e.g., hypoglycemia, glycemic variability, insulin sensitivity)." (PMID 38033011, 2023).
Hypoglycemia (continued). "One hypoglycaemia coma which was resolved after emergency management was reported in a patient in the saxagliptin group during trial, who was also administrated with multiple insulin injection." (PMID 37076476, 2023). "DD may also be related to side effects from the injection such as pain, fear of hypoglycemia, and difficulty in administering the insulin injection." (PMID 37250811, 2023). "In both cardiac and non-cardiac surgical patients, intensive insulin regimens aimed to achieve tighter blood glucose targets have found to not be beneficial and confer a high risk of hypoglycemia and increased glucose variability and hence not recommended." (PMID 37120562, 2023). "Hypoglycemia is especially a threat during the night in patients with insulin-treated T2D, which may lead to increased mortality, anxiety, poor adherence, and hypoglycemia unawareness." (PMID 36882852, 2023). "The use of CVII requires more nursing time for patient care, and there is a risk of hypoglycemia if the PN is stopped without stopping insulin infusion." (PMID 37674887, 2023). "This could be explained by an increase in insulin production from a high dietary sugar intake, which resulted in behavioral changes such as poor self-control due to reactive hypoglycaemia and poor glucose tolerance." (PMID 37143974, 2023). "Incredibly, the patch was effective in preventing an insulin overdose and consequent hypoglycemia." (PMID 37896204, 2023). "Analysis of β cell mass, islet endocrine cell-type composition, and pancreatic insulin content further ruled out β cell hyperplasia as underlying the hypoglycemia." (PMID 36821378, 2023). "Driving when insulin-treated comes with specific requirements, such as informing the driving licensing authority, monitoring glucose levels regularly while driving and keeping hypoglycemia treatment in the vehicle." (PMID 36197724, 2022). "To investigate the mechanism of insulin resistance in ricin-mediated hypoglycemia, we performed immunoblotting to determine whether insulin signaling in the liver was affected following ricin exposure." (PMID 36548717, 2022). "Furthermore, this study also found that both insulin use and CKD are independent factors for risk of hypoglycemia, with patients with advanced CKD who use insulin being at the highest risk for a hypoglycemic event." (PMID 35189851, 2022). "Negative health beliefs (cognitions) are common, including fear of injections, uncertainty around efficacy, fears around hypoglycemia, potential weight gain and misconceptions that starting insulin represents a poorer prognosis, or “the end of the road” in their treatment and condition." (PMID 36197724, 2022). "Tirzeptide apparently has no intrinsic risk for inducing hypoglycemia; in clinical studies, an increase in hypoglycemia incidence was only observed in tirzepatide-treated patients if they had a comedication with insulin and/or oral insulinotropic agents (sulfonylurea)." (PMID 36313764, 2022). "Remarkably, treating the control KKAa parental strain with SN-401 at the same treatment dose (5 mg/kg × 4–10 days) does not cause hypoglycemia, nor does it alter glucose and insulin tolerance." (PMID 35145074, 2022). "Second, switching to IDegLira, while maintaining the same basal insulin dose, was sufficient to obtain a superior therapeutic effect without causing undesirable side effects, such as nocturnal hypoglycemia or gastrointestinal symptoms." (PMID 35097130, 2022). "In insulin-deficient patients, ABA supplementation should improve and prolong the action of exogenous insulin, perhaps allowing them to reduce their daily dose of insulin (and the risk of hypoglycemia), while at the same time ameliorating glycemic control." (PMID 35736456, 2022). "Previous hypoglycemic drug and exogenous insulin administration reduces blood glucose levels regardless of the blood glucose levels in vivo, greatly increasing the risk of hypoglycemia." (PMID 36204104, 2022).
Hypoglycemia (continued). "Although early initiation of basal insulin therapy may confer beta-cell protection and decrease hepatic glucose production, there are barriers to insulin initiation that include fear of hypoglycaemia and weight gain." (PMID 36104712, 2022). "Of note, it has been reported that insulin resistance, lack of insulin or hypoglycemia associated automimic failure would affect glucose sensitivity of glucose-sensing neurons, thereby whole-body glucose homeostasis (see the review Ref." (PMID 35619170, 2022). "Development of hypoglycemia is estimated to be from 20 min to 10 h after exogenous insulin intake." (PMID 35324747, 2022). "An in vivo study showed that insulin-loaded PLGA-FA-CS nanocarriers were able to induce hypoglycemia in a sustained manner as compared to subcutaneously administered insulin, following which a spike in hypoglycemia was observed within two hours after administration." (PMID 35890301, 2022). "The first would be to include insulin-induced hypoglycemia to the stimuli under study." (PMID 36548712, 2022). "Monitoring insulin use using video consulting services may enhance patient care with frequent checks for hypoglycaemia episodes." (PMID 35172774, 2022). "Pancreatic β-cells are not overstimulated to secrete excessive insulin; thus, there is a lower risk of hypoglycemia." (PMID 35329796, 2022). "SC bihormonal artificial pancreas devices that utilise both insulin and glucagon can potentially allow more aggressive insulin treatment than unihormonal devices using only insulin, as glucagon could counteract insulin-induced hypoglycaemia." (PMID 36213069, 2022). "Higher insulin dosing combined with saturation of the line with insulin could result in overdosing and hypoglycaemia." (PMID 36542240, 2022). "The DUAL study VII compared the use of basal-bolus insulin versus IDegLira, showing the non-inferiority of the latter in declining HbA1c, with a lower risk of hypoglycemia and significant weight loss in contrast to weight gain in the basal-bolus group." (PMID 35573995, 2022). "A comparison of adding basal insulin to maintaining GLP-1RA and an indirect comparison between the two strategies were conducted on the change in HbA1c, fasting plasma glucose (FPG), target achievement [HbA1c < 7.0%], and the risk of confirmed hypoglycemia." (PMID 35669682, 2022). "We consider that nocturnal hypoglycemia in patients with BN observed in this study may have changed insulin antagonist hormone metabolism due to hypervagal activity during sleep." (PMID 36303193, 2022). "In addition, the McNemar χ2 test was performed on the occurrence of hypoglycemic events to evaluate the safety of this insulin dosage, indicating that the 1/6 scheme increased the incidence of hypoglycemia in patients (p = 0.039)." (PMID 35237639, 2022). "Patients expressed concerns about the side effects of insulin, especially that of hypoglycaemia episodes, which may potentially impact adherence if it occurs repeatedly.“Once the sugar level goes down, will start trembling badly." (PMID 35172774, 2022). "While insulin therapy is a known risk factor for hypoglycemic episodes, whether advanced CKD by itself is associated with increased risk of hypoglycemia has been controversial." (PMID 35189851, 2022). "Glucose course after glucagon injection might mimic an insulin-induced hypoglycemia state, characterized by rapid decrease of glucose levels, but without leading to absolute hypoglycemia." (PMID 35723775, 2022). "In addition, they directly stimulate α-cells to produce more glucagon in response to hypoglycemia and decrease insulin secretion." (PMID 35346357, 2022). "The onset, duration, and level of hypoglycemia depend on the dose and type of overdosed insulin." (PMID 35324747, 2022). "Insulin intoxications, being hypoglycemia-related deaths, could be successfully discriminated from hyperglycemic and presumed normoglycemic deaths by postmortem metabolomics and multivariate statistical modeling." (PMID 36676928, 2022).